KIF23 (kinesin family member 23)
Description:
Component of the centralspindlin complex that serves as a microtubule-dependent and Rho-mediated signaling required for the myosin contractile ring formation during the cell cycle cytokinesis. Essential for cytokinesis in Rho-mediated signaling. Required for the localization of ECT2 to the central spindle. Plus-end-directed motor enzyme that moves antiparallel microtubules in vitro.
Synonyms: KNSL5; MKLP1; MKLP-1; CDA3; CDAIII; CDAN3; CDAN3A; CHO1
Tractability: Small molecule: a structure with a bound ligand is known. PROTAC: UniProt records ubiquitination sites on it; ubiquitination databases record sites on it.
Target class: Other cytosolic protein
Gene: Protein-coding gene on chromosome 15 (69,414,246 to 69,448,427, forward strand). Ensembl gene ENSG00000137807.
Subcellular location: Nucleus; Cytoplasm, cytoskeleton, spindle; Midbody, Midbody ring; Midbody
Subcellular location (Human Protein Atlas): Nucleoplasm; Annulus; Mid piece; Midbody ring; Mitotic spindle; Principal piece
Pathways (Reactome):
Cell Cycle: Mitotic Telophase/Cytokinesis
Hemostasis: Kinesins
Immune System: MHC class II antigen presentation
Vesicle-mediated transport: COPI-dependent Golgi-to-ER retrograde traffic
Gene Ontology:
Molecular function: microtubule binding; protein binding; microtubule motor activity; ATP binding
Biological process: mitotic cytokinesis; mitotic spindle midzone assembly; positive regulation of cytokinesis; mitotic spindle elongation; microtubule-based movement
Cellular component: centralspindlin complex; centrosome; Flemming body; focal adhesion; midbody; mitochondrion; mitotic spindle; nucleoplasm; nucleus; spindle; cytosol; kinesin complex
Genetic constraint (gnomAD): Loss-of-function variants: 20 observed, 104.23 expected, observed/expected ratio (o/e) 0.19, 90% interval 0.13 to 0.28. The upper end of that interval is the gene's LOEUF score, 0.28, which puts it in group 1 of 6, group 1 being the genes least tolerant of losing a copy. Missense variants: 740 observed, 1,028.4 expected, observed/expected ratio (o/e) 0.72, 90% interval 0.68 to 0.76. Synonymous variants: 300 observed, 342.17 expected, observed/expected ratio (o/e) 0.88, 90% interval 0.8 to 0.96.
Homologues: Orthologues: macaque KIF23 (99% identical), chimpanzee KIF23 (98% identical), pig KIF23 (95% identical), dog KIF23 (94% identical), rabbit KIF23 (92% identical), mouse Kif23 (88% identical), rat Kif23 (87% identical), guinea pig KIF23 (80% identical), tropical clawed frog kif23 (72% identical), zebrafish kif23 (65% identical), Drosophila melanogaster pav (37% identical), Caenorhabditis elegans zen-4 (28% identical). Paralogues in human: KIF20A (22% identical), KIF13A (20% identical), KIF13B (19% identical), KIF1A (19% identical), KIF1B (18% identical), KIF21B (18% identical), KIF16B (18% identical), KIF5A (18% identical), KIF21A (18% identical), KIF5C (17% identical), KIF4A (17% identical), KIF15 (17% identical), and 29 more.
Diseases named in the same sentence as KIF23 in open-access papers:
KIF23 is named in the same sentence as 85 diseases in open-access papers, as found by Europe PMC text mining. Sharing a sentence is not in itself a finding about the gene and the disease. The quoted sentences say what the papers report.
breast carcinoma (27 papers, 2012 to 2025). "In a study that examined the association between members of the kinesin family and breast cancer, KIF23 and KIF11 were found to be associated with poor prognosis." (PMID 34675265, 2021). "KIF23 overexpression is significantly associated with tumor grade, invasion and prognosis in breast cancer." (PMID 30581678, 2018). "We found overexpression of KIF23 could partly reverse the decrease in breast cancer cells proliferation caused by the knockdown of FOXM1." (PMID 35524313, 2022). "Zou and colleagues verified that overexpression of KIF23 was significantly associated with prognosis in ER-positive breast cancer patients and that knockdown of KIF23 inhibited tamoxifen-sensitive and resistant breast cancer cell proliferation and induced apoptosis." (PMID 33754001, 2021). "Previous studies have also demonstrated KIF23's role in promoting the proliferation of various cancers, including breast cancer, bladder cancer, and hepatocellular cancer." (PMID 38514510, 2024). "KIF23 is involved in cell proliferation and differentiation and abnormally expressed in glioma, liver cancer, breast cancer and non-small cell lung cancer." (PMID 37483517, 2023). "Quantitative real-time PCR and Western blot were used to determine the KIF23 expression in breast cancer tissues and cell lines." (PMID 35524313, 2022). "In breast cancer datasets, KIF23 expression was significantly related to cell cycle and proliferation, which was confirmed by several datasets." (PMID 35524313, 2022). "KIF23 (kinesin family member 23) exerts a pro-tumor function in breast cancer by stimulating the Wnt/β-catenin pathway." (PMID 35954483, 2022). "Like DEPDC1B, KIF23 was overexpressed in various cancers, such as pancreatic cancer, breast cancer and primary lung cancer." (PMID 34983303, 2022). "KIF23 expression was also determined in different subtypes of breast cancer cell lines and normal human breast cell lines by qRT-PCR and western blot analysis." (PMID 35524313, 2022). "Some research shows that KIF23 is upregulated in a variety of tumors and is related to the occurrence and development of tumors, such as gastric cancer 9, glioma 10, breast cancer 11 and ovarian cancer." (PMID 33754001, 2021). "Ectopic expression of KIF20A promoted chemoresistance of CRC cells to oxaliplatin or 5-FU treatment by decreasing apoptosis 37 and also indicated that expression of KIF4A, KIF15, KIF20A and KIF23 was correlated with prognosis in breast cancer." (PMID 33995648, 2021). "KIF23 overexpression has been found in breast cancer, pancreatic cancer, primary lung cancer and prostate cancer, and also has been related with poor prognosis for several cancer types." (PMID 33726773, 2021). "Silencing of KIF23 expression strongly suppressed proliferation of MDA-MB-231 cells due to multinucleation and polyploidization, suggesting that KIF23 is a potential target for therapy of breast cancer." (PMID 28061449, 2017). "Similarly, in breast cancer, KIF23 promotes tumor cell proliferation and migration through the Wnt/β-catenin signaling pathway." (PMID 41138746, 2025). "In addition, in breast cancer, the upregulation of KIF23 has been shown to enhance cancer cell proliferation and promote malignant behavior, potentially mediated through the Wnt/β-catenin signaling pathway." (PMID 41138746, 2025). "The inclusion of three additional targets (CCNA2, PCNA, and KIF23) within the APIS BC Subtyping Kit, known to be associated with breast cancer proliferation and expressed across all cell cycle stages, allows for the generation of a more complete proliferation measure." (PMID 38337757, 2024). "Currently, KIF23 and KIF11 are under investigation as TNBC drug targets; KIF11 inhibition was previously shown to stall the tumor growth of breast cancer xenografts, while KIF23 drove TNBC migration, proliferation, and the metastasis-promoting epithelial–mesenchymal transition in vitro." (PMID 39409999, 2024).
breast carcinoma (continued). "The identification of KIF23 as a direct interactor of DDX5 might suggest that a similar mechanism could be present in breast cancer cells." (PMID 35954483, 2022). "KIF23 was reported to be overexpressed in pancreatic ductal adenocarcinoma, malignant pleural mesothelioma, lung cancer, breast cancer, hepatocellular carcinoma (HCC), gastric cancer, and ovarian cancer." (PMID 34017355, 2021). "KIF 11 and KIF23 are the well-studies KIF family members and considered as an oncogene, inhibition of which can cause arrest at mitosis exit in hepatocellular cell carcinoma, lung cancer, pleural mesothelioma, and glioma cancer, breast cancer, meningiomas." (PMID 34051812, 2021). "To determine whether these findings are of clinical significance, we asked whether expression of KIF23 and PRC1 is associated with prognosis of breast cancer by examining previously published microarray data sets." (PMID 28061449, 2017). "Elevated expression levels of kinesins KIF14, KIF4A, KIF20A, and KIF23, KIF2C, and KIFC1 have been reported in breast cancer cell lines, other kinesins KIF10, KIF18A, and KIF15 have been linked to prognostic indicators in breast cancer patients." (PMID 32346924, 2020). "We found that KIF23, KIF20A, KIF4A, KIFC1 and PRC1 were expressed at high levels in all investigated breast cancer cell lines." (PMID 28061449, 2017). "We next examined expression of KIF23 and PRC1 in breast cancer gene expression datasets grouped according to HU and PAM50 subtypes." (PMID 28061449, 2017). "As already shown in breast cancer, we also find several members of the Kinesin protein family (KIF11, KIF15, KIF23, KIF2C and KIFC1) to be upregulated in patients with high expression of ATAD2." (PMID 26308378, 2015). "Four showed centrosome amplification (KIAA0101, KIF14, KIF23 and HMMR) on the HeLa cell line and the breast cancer cell line Hs578T." (PMID 22956898, 2012). "Additionally, study found that 26 of 38 kinesins detected in breast cancer MCF-7 cells are regulated by estrogen 17β-estradiol (E2) and many of them are upregulated by E2, including KIF15, KIF4A, KIF20A, and KIF23." (PMID 31729978, 2019). "Inhibition of KIF23 and PRC1 had strong antiproliferative effects in breast cancer cells." (PMID 28061449, 2017). "KIF23 and PRC1 could be used as prognostic biomarker and could be potential therapeutic targets for the treatment of breast cancer." (PMID 28061449, 2017). "However, five genes (CDC20, MET, KIF23, ANXA1, and CASP1) that are found in the TNBC group were not highly expressed in the HR+ breast cancer subtypes but are commonly found in the ER−/PR+ and ER−/PR− groups such that they could be used as negative controls." (PMID 39000600, 2024).
glioma (27 papers, 2012 to 2025). A benign or malignant brain and spinal cord tumor that arises from glial cells (astrocytes, oligodendrocytes, ependymal cells). "To clarify this issue, we obtained point mutation and copy number alterations (CNAs) of KIF23 in 319 gliomas using whole-exome sequencing." (PMID 34017355, 2021). "Since higher expression of KIF23 was negatively associated with overall survival with patients, we further investigated the prognostic value of KIF23 amplification with 319 glioma samples." (PMID 34017355, 2021). "Given the idea that KIF23 is a novel prognostic biomarker with potential therapeutic implications in glioma, it is valuable to investigate the mutation and CNAs status of KIF23 in glioma." (PMID 34017355, 2021). "In this study, we screened for KIF23 DNA mutation and CNAs in 319 gliomas with DNA and RNA sequencing data, and demonstrated that elevated KIF23 expression in glioma was probably caused by DNA copy number amplification." (PMID 34017355, 2021). "Only two glioma samples with missense mutations in KIF23 coding region were identified, while 7 patients were detected with amplification of KIF23." (PMID 34017355, 2021). "In order to investigate KIF23 somatic mutation and CNAs in glioma, we then screened the 319 glioma samples by using whole-exome sequencing analysis from CGGA database." (PMID 34017355, 2021). "In this study, we evaluated the expression pattern, prognostic value and biological associations of KIF23 from RNA expression profilings of glioma samples, as well as from in vitro and in vivo assays." (PMID 27013586, 2016). "High KIF23 expression was shown to be a risk factor for glioma patients [P<0.01, HR 4.241, 95 % confidence interval (CI) 3.037-5.923]." (PMID 27013586, 2016). "The association of KIF23 expression with prognosis of glioma patients was investigated through Kaplan-Meier survival curve analysis with a log-rank test of 305 glioma patients in CGGA dataset." (PMID 27013586, 2016). "Case-specific non-synonymous mutation of KIF23 in 2 glioma samples." (PMID 34017355, 2021). "Thus, it was deduced that elevated KIF23 expression in glioma tended to be caused by DNA copy number amplification, instead of mutation." (PMID 34017355, 2021). "Moreover, pan-cancer analysis showed that gaining of copy number was significantly associated with higher expression of KIF23, consolidating our findings in glioma." (PMID 34017355, 2021). "Therefore, this evidence indicates KIF23 over-expression is associated with glioma malignancy and conferred a worse survival time in glioma, which suggests KIF23 is a new novel prognostic biomarker with potential therapeutic implications in glioma." (PMID 27013586, 2016). "However, KIF23 mutation and CNAs status in glioma is unclear." (PMID 34017355, 2021). "Furthermore, to evaluate whether KIF23 could act as an independent prognostic biomarker for glioma patients, we performed a stepwise, multivariate Cox regression analysis incorporating KIF23 expression, KPS score, age, tumor grade and IDH1 mutation status." (PMID 27013586, 2016). "Oncomine's comparative analysis between cancer and normal tissues revealed that both RRM2 and KIF23 were significantly overexpressed in glioma across various datasets, showcased in Fig.." (PMID 39248068, 2025). "The down-regulation of KIF23 was shown to suppress glioma proliferation, and it was therefore proposed as a potential therapeutic target for GBM." (PMID 37644431, 2023). "We got the similar results that KIF23 expression was the highest in grade IV glioma group, while had the lowest expression in grade II glioma group (p < 0.001)." (PMID 34017355, 2021). "In glioma, KIF23 was also showed to be up-regulated compared to normal brain samples, and inhibition of KIF23 suppressed the proliferation of glioma cells both in vivo and in vitro." (PMID 34017355, 2021). "This is consistent with what we have found in the analysis of expression of KIF23, consolidating the malignant role of KIF23 in glioma." (PMID 34017355, 2021).
glioma (continued). "KIF23 overexpression is a common event seen in various tumors, such as glioma, breast, and paclitaxel-resistant gastric cancer." (PMID 33800494, 2021). "Our previous study showed that KIF23 mRNA expression was positively correlated with glioma grade, and high KIF23 expression conferred poor survival in glioma, which was further validated by the TCGA, REMBRANDT, and GSE16011 database." (PMID 34017355, 2021). "In terms of the important role of KIF23 in tumorigenesis and malignant aggressive progression of glioma, further understanding of its functional mechanism and pathway should be investigated." (PMID 34017355, 2021). "Our results showed that KIF23 CNVs occurred in various human cancers, including endometrial carcinoma, melanoma and gliomas, suggesting KIF23 as a critical role in pan-cancer." (PMID 34017355, 2021). "As a member of the kinesin superfamily, KIF23 was highly expressed in many kinds of tumors, such as gliomas, ovarian cancer, and gastric cancer." (PMID 34268107, 2021). "Based on above features, up-regulated KIF23 has been considered as one of biomarkers in multiple tumors including lung cancer, malignant pleural mesothelioma, glioma and hepatocellular carcinoma." (PMID 32586319, 2020). "The identified DryNB included seven genes (KIF2C, CCNA2, NDC80, KIF11, KIF23, ANLN and CENPM) that were significantly associated with drug sensitivity or resistance of glioma patients to the targeted therapies." (PMID 31682596, 2019). "We also found a strong correlation between ANLN and KIF23, an independent prognostic target for glioma." (PMID 31681575, 2019). "KIF23 overexpression was significantly associated with high-grade glioma, as well as higher mortality, in survival analysis, and the downregulation of KIF23 was reported to suppress glioma proliferation." (PMID 30872592, 2019). "Given that KIF23 is vital for cytokinesis and its effects on cell growth, KIF23 is a possible therapeutic target in glioma." (PMID 27013586, 2016). "The analysis revealed that KIF23 expression was an independent prognostic factor for the overall survival of glioma patients." (PMID 27013586, 2016). "KIF23 was elevated in glioma tissues and cell lines compared to normal brains, and silencing KIF23 expression inhibited the growth of glioma cells both in vitro and in vivo." (PMID 27013586, 2016). "In order to explore the biological processes of KIF23 in glioma, KIF23 correlated genes were analyzed by Pearson correlation." (PMID 27013586, 2016). "In conclusion, our study showed that expression levels of KIF23 increasing with the ascending grade of glioma." (PMID 27013586, 2016). "This analysis revealed that KIF23 expression level was an independent prognostic factor for the overall survival of glioma patients." (PMID 27013586, 2016). "Kinesin family member 23 (KIF23), a nuclear protein and a key regulator of cellular cytokinesis, has been found to be overexpressed as an oncogene in glioma." (PMID 27013586, 2016). "In this study, we evaluated KIF23 expression pattern in 305 glioma samples of CGGA database, the results showed that KIF23 expression was positive correlated with tumor grades." (PMID 27013586, 2016). "In order to analyze KIF23 expression value in the different molecular subtypes of glioma, we annotated the 4 datasets using TCGA and CGGA classification systems by Prediction Analysis of Microarrays (PAM)." (PMID 27013586, 2016). "In glioma, silencing KIF23 inhibits the proliferation of glioma cells." (PMID 35478956, 2022). "In glioma, kinesin family member 23 (KIF23) is up-regulated and plays a vital role in oncogenesis." (PMID 34017355, 2021). "We then tested whether the temporal patterns of the prioritized 5 genes (i.e., KIF2C, CCNA2, NDC80, KIF11 and KIF23) could be used to predict drug sensitivities of different glioma cell lines." (PMID 31682596, 2019). "High expression of KIF23 in glioma cells may be related to transcriptional activation, and in vivo and in vitro experiments have demonstrated." (PMID 30581678, 2018).